CD33 (CD33 molecule)
Diseases named in the same sentence as CD33 in open-access papers (continued):
Sharing a sentence is not in itself a finding about the gene and the disease.
myeloid malignancies (14 papers, 2016 to 2025). "Even before the development of imatinib, the targeting of myeloid surface markers yielded the first precision drug in myeloid malignancies in 2000: the anti-CD33 antibody–drug conjugate (ADC) gemtuzumab ozogamicin (GO)." (PMID 39997326, 2025). "As the transmembrane glycoprotein CD33 is only expressed in myeloid cells and displays increased expression in multiple myeloid malignancies, it is inherently an attractive therapeutic target." (PMID 39997326, 2025). "A multicenter phase I/II study of a CD16/CD33/IL-15 TRiKE is ongoing for CD33+ myeloid neoplasms (NCT03214666)." (PMID 36613644, 2022). "Several monoclonal antibodies targeting CD 70, CD 45, CD 123, and CD33 are currently being investigated in myeloid neoplasms." (PMID 36009521, 2022). "Since CD33 constitutes a promising target for immunotherapy of myeloid malignancies, NK cells expressing a CD33-specific chimeric antigen receptor (CAR) were generated." (PMID 35058934, 2021). "Prior work in this field has focused solely on CD33, a myeloid antigen, confining the reach of this strategy to myeloid malignancies." (PMID 34423790, 2021). "This is of particular interest as CD33 has been considered a therapeutic target for myeloid malignancies, using either anti-CD33 monoclonal antibodies (gemtuzumab ozogamicin, lintuzumab, and vadastuximab talirine) or gene-edited stem cells." (PMID 33198164, 2020). "The first BiTE therapy developed in myeloid malignancies was against CD33 (AMG 330)." (PMID 34829860, 2021). "The two most studied targets for CAR-T therapies in myeloid malignancies are CD33 and CD123." (PMID 34829860, 2021). "There is a considerable concern regarding the inhibition of normal myelopoiesis during the development of novel CAR T cell therapies for myeloid malignancies based on the results of preclinical studies of scFv-based CAR T cells targeting CD33 or CD123 antigens." (PMID 26983639, 2016). "As potential application, here the authors describe the design and characterization of allogeneic CD33-targeting CAR-NKT cells, showing anti-tumor activity in preclinical models of bone marrow-resident myeloid malignancies." (PMID 39893165, 2025). "TriKE (161533) comprises two single-chain variable fragments (scFvs), one that binds to CD16 on NK cells and another that binds to CD33 on myeloid malignancies, plus an IL-15 linker bridging the CD16 and CD33 scFvs for sustained cell activation." (PMID 36830717, 2023). "When CD33 and CLL-1 CAR T cells were co-cultured with different myeloid tumor cells such as U937, THP-1 and HL60, all of them induced CAR down-regulation, however, THP-1 and MOLM-13 cell lines did not induce CAR down-regulation when they were co-cultured with CD123 CAR T cells." (PMID 38184596, 2024).
dementia (13 papers, 2012 to 2025). Loss of intellectual abilities interfering with an individual's social and occupational functions. "We recently identified the SNP rs2455069 in exon 2 of the human CD33 gene on chromosome 19, which is involved in an unusual familial form of dementia." (PMID 35408990, 2022). "However, CD33 gene expression was found to mediate the association between PTPN6 gene expression and clinical AD dementia." (PMID 39336795, 2024). "We recently identified the CD33 SNP rs2455069-A>G (R69G) in a familial form of dementia." (PMID 35408990, 2022). "Based on the evidence of the possible involvement in an unusual form of dementia of the SNP rs2455069-A>G in exon 2 of CD33 gene, leading to a change from arginine to glycine in position 69, we widened the analysis of this SNP to a cohort of AD patients from southern Italy." (PMID 35408990, 2022). "Notably, several dementia genes are linked to microglia/immune function (e.g. TREM2 and CD33)." (PMID 30252044, 2018). "A recent comprehensive Mendelian randomization study identified potential biomarkers in cerebrospinal fluid (CSF) and plasma for various types of dementia, including apolipoprotein ε2 (APOE2) for various dementias, Siglec-3 for AD in CSF, and CD33 for AD." (PMID 41465142, 2025). "In a comparative analysis of gene expression in MRI type 2, we found a decrease in the expression of ACOX1, BIN1, CD2AP, CD33, TNFR1, VEGFA, and VEGFC genes in clinically significant CI (MCI and dementia) compared to the control group." (PMID 39125683, 2024).
Sepsis (13 papers, 2015 to 2025). Sepsis is defined as life-threatening organ dysfunction caused by a dysregulated host response to infection. "Targeting this antigen as well as the immunosuppressive CD33 could be promising preventative targets in obese and diabetic patients at a high risk for sepsis and mortality." (PMID 36687421, 2022). "A so-called unconventional CD15+ CD11b+ CD14+ CD33+ CD66b+ HLA-DR− subset increased early during sepsis and returned to physiological levels in survivors." (PMID 38391927, 2024). "With increasing disease severity, we found a shift in the phenotype of cMono to lower expression of HLA-DR, CD33, and CD11c, and evidence of proliferating monocytes based on expression of Ki-67 and DNA abundance, with comparable changes in sepsis patients." (PMID 35216673, 2022). "Based on the gating strategy, expression of MDSCs (CD11b+CD33+HLADR−ve) was significantly increased (p = 0.011) in sepsis patients compared to w/o sepsis patients." (PMID 35720398, 2022). "According to the Cohen’s effect size scale, the decline in percentage of the CD14+ monocytes and the CD33+ monocytes constituted the most significant parameters in obese patients suffering from sepsis including septic shock." (PMID 36687421, 2022). "In summary, increasing pro-inflammation with the transition of sepsis to septic shock appears to be associated with lower CD14+ and CD33+ and up-regulation of CD16, particularly in obese patients." (PMID 36687421, 2022). "In support of translating the mechanistic concept to human sepsis, we found that Hotairm1 binds S100A9 protein in CD33+CD11b+HLA-DR− MDSCs during established sepsis." (PMID 33335790, 2020). "Only at or after 14 days following sepsis onset did the isolated CD33+CD11b+HLA-DRlow/− cells display the T cell-suppressive activity required to be classified as MDSCs." (PMID 31722736, 2019). "Flow cytometric analysis revealed that septic patients (n = 211) 4 days following sepsis had a median percentage (relative population) of 22.4% CD33+CD11b+HLA-DRlow/−CD14+ M-MDSCs and 7.9% CD33+CD11b+HLA-DRlow/−CD14− G-MDSCs." (PMID 31722736, 2019). "Given that our mice developed a substantial percentage of CD33+ cells, they appear adequately competent to recapitulate such a response to sepsis." (PMID 26272069, 2015). "Moreover, the proportion of CD33+ monocytes was even lower in septic shock when compared to sepsis in diabetic patients." (PMID 36687421, 2022). "Finally, we assessed the more differentiated population of human cells; CLP-induced sepsis led to a 3.5-fold reduction of CD33+ myeloid cells (16.98 % versus 4.89 %, P < 0.05), but the impact of sepsis on CD20+ B cells was insignificant." (PMID 26272069, 2015). "Despite similar changes of the monocyte subsets including CD14+ and CD33+ in obese septic patients with diabetes, CD16 expression densities were higher in sepsis patients than in the non-sepsis group." (PMID 36687421, 2022). "In all patients developing sepsis and septic shock, monocytes as well as CD14+, CD33+, CD14+CD16–, and CD14–CD16+ were significantly reduced (p < 0.05), which is in line with the previous report." (PMID 36687421, 2022). "It should be noted that no other basal differences between sepsis and healthy monocytes were found in membrane markers or cytokine levels, except for a slight decrease in CD33 in sepsis monocytes." (PMID 37047205, 2023). "Non-diabetic sepsis patients further presented with decreased CD33 and up-regulated CD163 expression density, which was absent in diabetic patients." (PMID 36687421, 2022). "This subpopulation of isolated CD33+CD11b+HLA-DRlow/− that were non-granulocytic, non-monocytic in nature was not described in our previous work on human MDSCs in sepsis." (PMID 31722736, 2019). "Much to our surprise, CD33+CD11b+HLA-DRlow/− cells isolated on day 4 after sepsis displayed a stimulatory, rather than suppressive, effect on lymphocyte proliferation to CD3/CD28 stimulation." (PMID 31722736, 2019).
Sepsis (continued). "However, the role of CD33 in sepsis with and without diabetes, including the relevance of hyperglycemia, remains ill defined." (PMID 36687421, 2022). "In the absence of diabetes and obesity, the negative impact of sepsis including septic shock on CD14+ and CD33+ monocytes were more moderate (ds = −0.3 to −0.8) when compared with obese diabetic patients (ds = −1.0)." (PMID 36687421, 2022).
glioblastoma (12 papers, 2011 to 2025). The most malignant astrocytic tumor (WHO grade IV). "Concerning glioblastoma (glioma grade IV, GBM), previous works reported the expansion of subsets of MDSCs and an association of levels of CD11+/CD33+/HLA-DRlow/− MDSCs with survival." (PMID 35069595, 2021). "Indeed, sialic acid-binding immunoglobulin-like lectin-H (Siglech) is a CD33-related Siglec that is a microglial sensor of glioblastoma cells." (PMID 32299465, 2020). "Genetic deletion or antibody blockade of SIRPα, CD22, CD33 and PD1 enhance the microglial phagocytic activities against Aβ and glioblastoma, making the receptors attractive therapeutic targets for treating AD and brain tumor." (PMID 37483607, 2023). "However, due to the highly heterogeneous nature of glioblastoma, characterized by variations in immune features and treatment responses among individuals, further in-depth experimental and clinical research is required to ascertain the precise role of CD33 in GBM." (PMID 38742049, 2024). "It is not known if CD33, like Siglech, is also a sensor of glioblastoma cells." (PMID 32299465, 2020).
glioma (12 papers, 2011 to 2025). A benign or malignant brain and spinal cord tumor that arises from glial cells (astrocytes, oligodendrocytes, ependymal cells). "We transfected these upregulated miRNAs into CD33+HLA-DR− MDSCs derived from glioma patients and measured CD73 expression." (PMID 37481646, 2023). "The Spearman correlation analysis results suggested that the immune marker sets of Treg (FOXP3, CCR8, TGFβ1), TAM (CCL2, CD68, IL-10), and MDSC (CD33, ITGAM, FUT4) were significantly associated with the PROS1 expression in glioma." (PMID 36685506, 2022). "According to the recent hypothesis, glioma immune escape is facilitated by inhibitory CD33-related Siglecs that interact with sialic acid on malignant cells and trigger a reduced activation response, resulting in an improved survival of glioma cells." (PMID 34299113, 2021). "To determine whether our findings are clinically relevant, we stained glioma tissue sections (n = 50) for BATF2, SDF-1α, HIF-1α (hypoxia marker), CD14 (Mo-MDSCs marker), and CD33 (MDSCs marker)." (PMID 33452462, 2021). "In many solid tumors, including gliomas, CD11b+CD14+CD33+HLA-DR−/lowCo-receptor−/low monocyte-MDSCs (M-MDSC), CD11b+CD15+CD33+Lin−HLA-DR−/low polymononuclear-MDSCs (PMN-MDSC), and a more immature subset of CD3−CD14−CD15−CD19 −CD56−CD33+CD11b+ early-MDSCs (e-MDSC) were described." (PMID 30987226, 2019). "Therefore, we assessed the expression of the different Siglec family members on sorted M-MDSCs (CD33+ MHC IIlow/− CD14+) and PMN-MDSCs (CD33+ MHC IIlow/− CD15+) from the blood of glioma patients." (PMID 30953118, 2019). "We performed single-cell transcriptomic analysis on the orthotopic glioma mouse model (GSE246154) from the GEO database using R. The results indicated that the Ifnar2 gene was enriched in T cells, while the CD68 and CD33 genes were less enriched in macrophages." (PMID 40297576, 2025).
gastric cancer (10 papers, 2013 to 2021). A primary or metastatic malignant neoplasm involving the stomach. "High CD8/CD33 ratio and high infiltration of CD8+ lymphocytes into peritoneal metastatic lesions were associated with favorable prognosis in gastric cancer patients with peritoneal metastasis." (PMID 33793095, 2021). "MDSCs commonly express the cell surface marker CD33 and CD11b, and CD33 positive cells in advanced gastric cancer correlated with worse prognosis." (PMID 33793095, 2021). "Concomitant with our findings, a poor prognosis and reduced survival of advanced gastric cancer are correlated with an increased CD33+CD11b+CD15+CD14-expressing PMN-MDSC infiltration." (PMID 34944780, 2021). "A number of studies relating to gastric cancer (GC) have reported MDSCs phenotype markers, including CD11b+, CD33+, CD14+, CD15+and HLA-DR-26,27." (PMID 32415175, 2020). "Analyzed by flow cytometry, CD11b+CD33+HLA- MDSCs percentages in peripheral blood were found to be significantly elevated in gastric cancer patients (6.93 ± 1.30 %) than control subjects (1.92 ± 0.77 %, p<0.001)." (PMID 33247701, 2020). "The results showed that the density of CD8+ T cells, CD20+ B cells, and CD33+/p-STAT1+ cells in tumors was a useful criterion for the prediction of survival in advanced gastric cancer patients." (PMID 23307253, 2013). "For this reason, CD33+/p-STAT1+ cells are defined as a specific type of MDSC in gastric cancer tissues, although further functional analysis is required." (PMID 23307253, 2013). "To characterize MDSC infiltration in gastric cancer tissue, we defined MDSCs as CD33+/p-STAT1+ cells." (PMID 23307253, 2013). "Similarly, increased levels of CD11b+CD33+HLA-DR−Lin−/low MDSC were shown as an independent prognostic factor in pancreatic, oesophageal, and gastric cancers and were associated with an increased risk of death." (PMID 25436215, 2014). "Here, our data confirms CD163 in gastric cancer has a positive correlation with Tregs (CD4, CD25 and FOXP3), MDSCs (CD33, CD11b and CD14) and Cafs (FAP), indicating CD163 level is an potential index to monitor the status of tumor associated macrophages, Tregs, MDSCs and Cafs in gastric cancer." (PMID 29152078, 2017). "Therefore, CD33+/p-STAT1+ cells were proposed to be a subset of MDSCs in gastric cancer tissues." (PMID 23307253, 2013). "High CD8/CD33 ratio and high infiltration of CD8+ lymphocytes in peritoneal metastatic lesions were favorable prognoses for gastric cancer patients with peritoneal metastasis." (PMID 33793095, 2021). "Since there are no consensus cell surface markers for putative cancer stem cells in gastric cancer, we examined changes in the following markers: CD24, CD33, CD44, CD90 and CD133 that are reported in the literature." (PMID 28404967, 2017). "This study examined the relationship between the survival rate of gastric cancer and the density of immune cells, including TILs and CD33+/p-STAT1+ cells, which represented MDSCs, to evaluate the role of the immune response in gastric cancer progression." (PMID 23307253, 2013). "In related studies on gastric cancer, granulocytic MDSCs with CD15, CD66 and CD33 markers." (PMID 32415175, 2020). "Overall, this study demonstrated that the density of CD33+/p-STAT1+ cells is an independent prognostic factor for patients with stage IIIa gastric cancer, indicating that CD33+/p-STAT1+ cells play a central role in the local immune response in gastric cancer." (PMID 23307253, 2013). "This study examined the relationship between gastric cancer survival and the density of immune cells, including CD8+ T cells, CD20+ B cells, and CD33+/p-STAT1+ cells, which represent myeloid-derived suppressor cells, to evaluate the role of immune cells in the progression of gastric cancer." (PMID 23307253, 2013). "The correlation between HMGB1 and CD68 has been observed in gastric cancer, but the correlation between HMGB1 and CD163 and CD33 has not been reported." (PMID 34257571, 2021).
gastric cancer (continued). "These CD33+/p-STAT1+ double-positive cells have been found mostly in the stroma among gastric cancer, whereas they had not yet been observed in the normal mucosa adjacent to gastric cancer and normal mucosa far from the gastric cancer (data not shown)." (PMID 23307253, 2013).
cervical cancer (9 papers, 2011 to 2022). A primary or metastatic malignant neoplasm involving the cervix. "Here, we aim to explore the associations between the levels of METTL3 and CD33+ myeloid-derived suppressor cells (MDSCs) in tumour tissues and the survival of patients with cervical cancer (CC)." (PMID 33059689, 2020). "The level of METTL3 is positively correlated with CD33+MDSCs in cervical cancer (CC) patients, and both METTL3 and CD33+MDSCs are independent prognostic factors for CC." (PMID 36439186, 2022). "Some scientists have demonstrated that elevated expression of METTL3 promotes the proliferation of CD33+ MDSCs, leading to the progression of cervical cancer." (PMID 35864471, 2022). "Significantly higher numbers of tumor-infiltrating MDSC (CD33+ cells) were observed in the lymph nodes from TRL-positive cervical cancer patients than in those from TRL-negative cervical cancer patients." (PMID 32170086, 2020). "To confirm the association between MDSCs and ALDH-high tumor cells in human cervical cancer specimens, we conducted immunohistochemical analyses of CD33 and ALDH1 expression using biopsy samples that were obtained at the initial diagnosis." (PMID 30555631, 2018). "As can be seen, significantly higher numbers of MDSCs, i.e. CD11b CD33+ HLA-DR-cells, were observed in patients in the higher-BAR group of patients with cervical cancer than patients in the lower-BAR group." (PMID 33500424, 2021). "Consistent with the findings obtained in mice, the peripheral blood of the cervical cancer patients with elevated serum G-CSF levels contained significantly higher numbers of MDSC; i.e., CD11b+ CD33+ HLA-DR− cells." (PMID 26666576, 2015). "To determine whether MDSCs played a role in the progression of cervical cancer, we sought the frequency of tumor-infiltrating MDSCs defined as HLADR−/low CD33+ CD11b+ population." (PMID 35688951, 2022). "COX2 expression was also elevated in many of the MDSC-inducing cell lines, particularly ovarian and cervical cancer cell lines, and PGE2 in combination with GM-CSF induced weak suppressive function in CD33+ cells (, data not shown)." (PMID 21658270, 2011).
hepatocellular carcinoma (9 papers, 2015 to 2025). A malignant tumor that arises from hepatocytes. "On the other hand, human M-MDSCs have been described as CD14+HLA-DR−(CD33+Lin−) in hepatocellular carcinoma, metastatic prostate cancer, renal cell cancer, and malignant melanoma." (PMID 26078490, 2015). "Circulating CD33+ cells, CD33+HLA-DR−, or CD33+HLA-DR−Lin− are described to be MDSCs in patients with renal cell cancer, colorectal cancer, or hepatocellular carcinoma, respectively." (PMID 26078490, 2015). "Furthermore, CD36+ cancer-associated fibroblasts (CAFs) employ MIF and CD74 to attract CD33+ myeloid-derived suppressor cells (MDSCs), creating an immunosuppressive environment that facilitates immune evasion in hepatocellular carcinoma." (PMID 40051627, 2025). "Ultimately, we found that the expression of hepatic CD11b+CD33+ MDSCs was increased in chronic liver diseases such as autoimmune hepatitis and hepatocellular carcinoma and positively correlated with the liver stages of hepatitis activity or liver fibrosis stage." (PMID 33860040, 2021). "In accordance with our study, other group reported that the frequency of circulating CD33+HLA-DRlow/−CD11b+CD14+PD-L1+MDSCs increased in hepatocellular carcinoma (HCC) patients versus controls." (PMID 32487171, 2020).